GOLGA8M (golgin A8 family member M)
Tractability: No criterion of Open Targets' tractability assessment is met for any kind of drug.
Gene: Protein-coding gene on chromosome 15 (28,698,583 to 28,738,384, reverse strand). Ensembl gene ENSG00000188626.
Gene Ontology:
Biological process: Golgi organization
Cellular component: cis-Golgi network; Golgi cis cisterna; Golgi cisterna membrane; Golgi apparatus
Genetic constraint (gnomAD): Loss-of-function variants: 31 observed, 41.88 expected, observed/expected ratio (o/e) 0.74, 90% interval 0.56 to 1. The upper end of that interval is the gene's LOEUF score, 1, which puts it in group 4 of 6, group 1 being the genes least tolerant of losing a copy. Missense variants: 355 observed, 346.37 expected, observed/expected ratio (o/e) 1.02, 90% interval 0.94 to 1.12. Synonymous variants: 126 observed, 129.73 expected, observed/expected ratio (o/e) 0.97, 90% interval 0.84 to 1.13.
Homologues: Orthologues: mouse Golga2 (45% identical), dog GOLGA2 (44% identical), tropical clawed frog golga2 (34% identical), zebrafish golga2 (29% identical), Drosophila melanogaster GM130 (22% identical), Caenorhabditis elegans golg-2 (19% identical), rat Golga2l1 (5% identical). Paralogues in human: GOLGA8J (97% identical), GOLGA8H (96% identical), GOLGA8K (96% identical), GOLGA8T (96% identical), GOLGA8N (92% identical), GOLGA8O (92% identical), GOLGA8Q (92% identical), GOLGA8R (92% identical), GOLGA8S (86% identical), GOLGA8F (81% identical), GOLGA8G (81% identical), GOLGA8A (67% identical), and 6 more.
Diseases named in the same sentence as GOLGA8M in open-access papers:
GOLGA8M is named in the same sentence as 3 diseases in open-access papers, as found by Europe PMC text mining. Sharing a sentence is not in itself a finding about the gene and the disease. The quoted sentences say what the papers report.
autoimmune disease (1 paper, 2022). A disorder resulting from loss of function or tissue destruction of an organ or multiple organs, arising from humoral or cellular immune responses of the individual to their own tissue constituents. "Furthermore, the importance of some features like GOLGA8M and SLC24A5 has been stated in the other viral infections or autoimmune diseases." (PMID 35922752, 2022).
cancer (1 paper, 2020). A tumor composed of atypical neoplastic, often pleomorphic cells that invade other tissues. "GOLGA8M encodes golgin A8 family member M. Although it has not been linked to cancer, a study suggested that palindromic GOLGA8 core duplicons promoted chromosome microdeletion and evolutionary instability." (PMID 32393195, 2020).
GOLGA8M also shares sentences with these, for which no sentence is quoted: viral infections (1 paper).